GART (phosphoribosylglycinamide formyltransferase, phosphoribosylglycinamide synthetase, phosphoribosylaminoimidazole synthetase)
Description:
Trifunctional enzyme that catalyzes three distinct reactions as part of the 'de novo' inosine monophosphate biosynthetic pathway.
Synonyms: GARS; AIRS; PGFT; PRGS; GARS-AIRS-GART; GARTF; PAIS
Tractability: Small molecule: an approved drug acts on it; a structure with a bound ligand is known; a high-quality ligand is known; it has a high-quality binding pocket; it belongs to a druggable protein family. PROTAC: ubiquitination databases record sites on it; its protein half-life has been measured; a small molecule that binds it is known.
Target class: Enzyme; Ligase
Chemical probes: AGF-94, CHEMBL365307, LOMETREXOL, PD081777, PD134464
Gene: Protein-coding gene on chromosome 21 (33,503,371 to 33,543,524, reverse strand). Ensembl gene ENSG00000159131.
Subcellular location (Human Protein Atlas): Cytosol; Mitochondria
Pathways (Reactome):
Metabolism: Purine ribonucleoside monophosphate biosynthesis
Gene Ontology:
Molecular function: phosphoribosylformylglycinamidine cyclo-ligase activity; phosphoribosylglycinamide formyltransferase activity; phosphoribosylamine-glycine ligase activity; ATP binding; catalytic activity; metal ion binding
Biological process: 'de novo' AMP biosynthetic process; 'de novo' IMP biosynthetic process; 'de novo' XMP biosynthetic process; GMP biosynthetic process; adenine biosynthetic process; purine nucleotide biosynthetic process; purine ribonucleoside monophosphate biosynthetic process; brainstem development; cerebellum development; cerebral cortex development; purine nucleobase biosynthetic process
Cellular component: cytosol; extracellular exosome
Genetic constraint (gnomAD): Loss-of-function variants: 35 observed, 93.63 expected, observed/expected ratio (o/e) 0.37, 90% interval 0.28 to 0.5. The upper end of that interval is the gene's LOEUF score, 0.5, which puts it in group 2 of 6, group 1 being the genes least tolerant of losing a copy. Missense variants: 1,065 observed, 1,202.1 expected, observed/expected ratio (o/e) 0.89, 90% interval 0.84 to 0.93. Synonymous variants: 422 observed, 429.47 expected, observed/expected ratio (o/e) 0.98, 90% interval 0.91 to 1.07.
Homologues: Orthologues: chimpanzee GART (99% identical), macaque GART (95% identical), dog GART (91% identical), pig GART (89% identical), rabbit GART (89% identical), rat Gart (87% identical), mouse Gart (86% identical), guinea pig GART (86% identical), zebrafish gart (60% identical), Drosophila melanogaster Gart (49% identical), Caenorhabditis elegans F38B6.4 (43% identical).